TRABD2A (TraB domain containing 2A)
Description:
Metalloprotease that acts as a negative regulator of the Wnt signaling pathway by mediating the cleavage of the 8 N-terminal residues of a subset of Wnt proteins. Following cleavage, Wnt proteins become oxidized and form large disulfide-bond oligomers, leading to their inactivation. Able to cleave WNT3A, WNT5, but not WNT11. Required for head formation.
Synonyms: C2orf89; TIKI1; LOC105374836
Tractability: Antibody: UniProt places it where antibodies can reach, with high confidence; its Gene Ontology location is reachable by antibodies, with high confidence; UniProt predicts a signal peptide or a membrane-spanning region. PROTAC: ubiquitination databases record sites on it.
Gene: Protein-coding gene on chromosome 2 (84,821,650 to 84,907,008, reverse strand). Ensembl gene ENSG00000186854.
Subcellular location: Cell membrane; Membrane raft
Gene Ontology:
Molecular function: endopeptidase activity; metalloendopeptidase activity; Wnt-protein binding
Biological process: negative regulation of Wnt signaling pathway; proteolysis; head development; positive regulation of protein-containing complex assembly
Cellular component: organelle membrane; plasma membrane; plasma membrane raft; membrane; membrane raft
Genetic constraint (gnomAD): Loss-of-function variants: 46 observed, 46.47 expected, observed/expected ratio (o/e) 0.99, 90% interval 0.78 to 1.27. The upper end of that interval is the gene's LOEUF score, 1.27, which puts it in group 5 of 6, group 1 being the genes least tolerant of losing a copy. Missense variants: 642 observed, 648.41 expected, observed/expected ratio (o/e) 0.99, 90% interval 0.93 to 1.06. Synonymous variants: 269 observed, 260.03 expected, observed/expected ratio (o/e) 1.03, 90% interval 0.94 to 1.14.
Homologues: Orthologues: chimpanzee TRABD2A (99% identical), macaque TRABD2A (94% identical), dog TRABD2A (88% identical), rabbit TRABD2A (87% identical), tropical clawed frog trabd2b (64% identical). Paralogues in human: TRABD2B (58% identical).
Diseases named in the same sentence as TRABD2A in open-access papers:
TRABD2A is named in the same sentence as 8 diseases in open-access papers, as found by Europe PMC text mining. Sharing a sentence is not in itself a finding about the gene and the disease. The quoted sentences say what the papers report.
endometriosis (1 paper, 2025). The growth of functional endometrial tissue in anatomic sites outside the uterine body. "Wnt protein binding (GOMF) was a significant pathway in our gene set analyses, with five genes overlapping with our biologically-implicated endometriosis gene set: CTHRC1 (mSMR), FZD6 (fibroblast-eSMR), PTPRO (fibroblast-, ovary-, and whole blood-TWAS), RECK (fibroblast-sSMR), and TRABD2A (mSMR)." (PMID 41377979, 2025).
endothelial dysfunction (1 paper, 2023). In vascular diseases, endothelial dysfunction is a systemic pathological state of the endothelium (the inner lining of blood vessels) and can be broadly defined as an imbalance between vasodilating and vasoconstricting substances produced by (or acting on) the endothelium. "In light of the literature, our finding of the genetic variants in the TMSB10/TRABD2A locus appears to support the role of endothelial dysfunction in CFZ-CVAE." (PMID 37408649, 2023).
ovarian carcinoma (1 paper, 2023). A malignant neoplasm originating from the surface ovarian epithelium. "We carried out differential gene expression analysis between ovarian cancer and healthy ovarian tissues for each cell population, and found that C1orf60, TRABD2A, CAND2 and other genes were significantly up-regulated genes in multiple clusters." (PMID 37124501, 2023).
cancer (1 paper, 2021). A tumor composed of atypical neoplastic, often pleomorphic cells that invade other tissues. "For example, the transcript with the largest PSI difference, ENST00000409520, is encoded by the TraB domain containing 2A (TRABD2A) gene associated with negative regulation of the Wnt signalling pathway, itself heavily implicated in cancers." (PMID 34469537, 2021).
TRABD2A also shares sentences with these, for which no sentence is quoted: cardiovascular diseases (1 paper); glioma (1); heart failure (1); multiple myeloma (1).